CD44 (CD44 molecule (IN blood group))
Diseases named in the same sentence as CD44 in open-access papers (continued):
Sharing a sentence is not in itself a finding about the gene and the disease.
tumor (continued). "Additionally, the collagen-CD44 axis plays a key role in mediating interactions between fibroblasts and various immune cells, facilitating the directional migration of immune cells away from the tumor parenchyma and toward the tumor stroma." (PMID 41031085, 2025). "Clinical studies suggest patients with CD44s-positive tumors may benefit from HA–irinotecan, while HA-based nanocarriers in CD44-overexpressing tumors enhance drug delivery, increase therapeutic efficacy with low cytotoxicity, inhibit tumor growth, and enable targeted chemotherapy." (PMID 40363706, 2025). "However, other studies have demonstrated that CD44 expression is dispensable for tumor metastasis." (PMID 39851489, 2025). "Interestingly, CSCs may have a unique expression pattern of CD44 isoforms depending on the tumor type." (PMID 39851489, 2025). "Thus, several studies have isolated the CD44 protein as part of tumor exosomes." (PMID 41440277, 2025). "In contrast, HPV-negative tumor cells presented elevated CD44 expression, which is consistent with prior transcriptomic data, suggesting a more transformed and stem-like phenotype that may contribute to their reduced clinical response and resistance to therapy." (PMID 41254766, 2025). "PTEN as a tumor suppressor impeded the self-renewal capacity and non-anchorage-dependent growth potential of LCSCs while diminishing the expression of stemness-associated genes, including CD44, ALDH1, Bmi1, Sox2, and Oct4, thus attenuating LCSC stemness." (PMID 40710326, 2025). "The underlying mechanism for this paradoxical effect may relate to the disruption of CD44’s normal function in maintaining cell–cell adhesion; its loss could facilitate an epithelial–mesenchymal transition (EMT), thereby promoting tumor cell invasion and dissemination." (PMID 41514534, 2025). "Interestingly, these findings suggest that the expression of CD44 isoforms may dynamically shift in response to changes in the tumor microenvironment." (PMID 40259468, 2025). "Focusing on T- cell and tumor cell states within different neighborhoods, in the Fibroblast-Enriched neighborhood, T- cells presented downregulation of activation markers, including CD44, CD45RO, HLA-A, ICOS, and Granzyme B, suggesting that fibroblasts play an immunosuppressive role." (PMID 41254766, 2025). "Thus, some studies demonstrate that, on the one hand, CD44 expression is necessary for tumor initiation and metastatic activity, and on the other hand, suppression of CD44 expression may be beneficial for tumor progression." (PMID 39851489, 2025). "Finally, CD44 has been demonstrated to interact with EGFR phosphorylation and activation in vitro in HNSCC cells, and it has been observed that a decrease in CD44 levels is associated with a reduction in p-EGFR and tumor growth." (PMID 40738059, 2025). "In addition, we also analyzed CD-44 as a known tumor biomarker for proliferation in cancer." (PMID 40770117, 2025). "Although no studies described the role of CD44 in the immune cell-derived exosomes, it is known that CD44 expresion in tumor-derived exosomes facilitate tumor migration and invasion, CD44 expression on NK/CAR-NK-derived exosomes might improve immune cell infiltration in the tumor microenvironment." (PMID 40806778, 2025). "Moreover, at cut-off value ≥5% tumour cells with positive immunostaining, the expression CD44 was found to be accompanied by the co-expression with individual members of the HER family as well as EGFRvIII (83%), CD109 (16%), HER2/EGFRvIII (65%), or HER2/HER4/EGFRvIII (55%)." (PMID 40227788, 2025). "The macrophage migration inhibitory factor (MIF), and its interacting partners CD74 and CD44 were highlighted, recognized for their roles in injury protection, healing promotion, and B cell survival, plays a pervasive role in mediating communications between tumor cells and macrophages." (PMID 40036264, 2025).
tumor (continued). "The differential interactome composition indicates a functional shift in EGFR signaling that may drive increased tumor cell adhesion (CD44, ITGB1, FN1), metabolic adaptation (GAPDH, ENO1) and stress response (HSPA4, HSP90AB1), consistent with mechanisms observed in therapy‐resistant CRC phenotypes." (PMID 41319168, 2025). "Compared with adjacent non-tumor liver tissue, clinical studies have shown that HCC commonly exhibits peritumoral or stromal HA enrichment together with increased expression of HA receptors, particularly CD44 and RHAMM, features linked to invasion, immune suppression, and poorer outcomes." (PMID 41155434, 2025). "Indeed, in our IF stainings, both CD44 and CRYAB specifically stained GTCs in both GTC-high and GTC-low tumor samples and the number of CD44+ or CRYAB+ cells were significantly higher in GTC-high tumors (Wilcoxon rank sum test, two-sided; p = 0.00666, p = 0.00524, respectively)." (PMID 39880824, 2025). "The Cd44 gene encodes a cell surface glycoprotein that plays a crucial role in BC metastasis through its involvement in cell adhesion, EMT, cancer stem cell maintenance, survival, invasion, and immune evasion and is associated with aggressive tumor behavior and poor clinical outcomes." (PMID 40806360, 2025). "Researchers have developed a polymeric chitosan-coated nanoparticle encapsulated with doxorubicin capable of binding specifically to CD44 receptors, thereby eliminating CD44+ cancer stem-like cells and reducing tumor size and cytotoxicity without causing systemic toxicity." (PMID 40548119, 2025). "Notably, CD44 was highly expressed on the tumor-enriched stressed CD56bright state, alongside CXCR4 and CD74, possibly sensitizing this population to TME-mediated immunosuppression from CAFs, fibroblasts, endothelial and tumor cells, as noted by high scores for TGF-β signaling, hypoxia and ROS." (PMID 38956379, 2024). "On the other hand, CD133 expression was significantly associated with CD44 expression (p = 0.004, OR: 9.778, 95% CI: 1.762–54.263), L1CAM expression (p = 0.024, OR: 4.714, 95% CI: 1.178–18.861) and marginally associated with moderately differentiated tumor histology." (PMID 39148690, 2024). "Additionally, a nanosystem targeting CD44, composed of d‐α‐tocopherol polyethylene 1000 glycol succinate and CS dual‐modified lipid‐albumin, was found to deliver paclitaxel into multidrug‐resistant tumor cells, thereby overcoming drug resistance." (PMID 38783892, 2024). "In addition to alterations in cell adhesion, the release of β-catenin from adherens junctions between cells is associated with the loss of cell–cell junctions and increased expression of target genes that promote tumour progression, such as CD44, cyclin D, and c-Myc." (PMID 39456984, 2024). "Furthermore, disulfidptosis activity also showed tight correlations with tumors at scRNA‐seq, and pairs, such as MIF_CD74_CD44, MIF_CD74_CXCR4, MDK_NCL, and APP_CD74, might be potential targets in disulfidptosis‐related tumor microenvironment." (PMID 38420162, 2024). "The present data support AR42 regulation of cell proliferation genes resulting in enhanced tumor cell clearance when paired with various cytotoxic agents, such as pazopanib, cisplatin, or decitabine, and the sensitization of MM cells to lenalidomide through CD44 upregulation." (PMID 39063110, 2024). "Additionally, an increase in survivin and CD44 expression showed its involvement in stemness and metastatic properties, which could be the basis of drug resistance and tumor relapse." (PMID 39456585, 2024). "A comparison of tumor and peritumor tissues showed that during oncotransformation in both studied groups, there were similar processes: the expression levels of keratins 4 and 13 were reduced, while the expression levels of keratin 17 and CD44 were significantly increased." (PMID 38540309, 2024).
tumor (continued). "To assess whether changes in the efficacies of the different treatment regimens correlate to differences in the immune cell composition of the tumor after treatment, we quantified the amount of tumor-infiltrating effector T cells (CD8+ CD44+) on day 7 after tumor IR." (PMID 38951172, 2024). "In addition, CD44+ cells were reported to stimulate tumor angiogenesis in HNSCC." (PMID 38783892, 2024). "In tumors with increased expression of CD44, the using of HA‐based nanocarriers was reported to have the benefits in the enhancement of drug delivery, the increase therapeutic efficacy with low cytotoxicity, the inhibition of tumor growth, as well as the high potential for targeted chemotherapy." (PMID 38783892, 2024). "The CD44 is a cell adhesion molecule that attaches to ligands in the connective tissue like hyaluronic acid, osteopontin, and matrix metalloproteinase, thereby increasing the degradation of cell-matrix junctions, which is an important event for the tumor cells to invade the connective tissue." (PMID 39050298, 2024). "Furthermore, CD44 is associated with the dysregulation of the Wnt/β-catenin signaling pathway, which is more active in CD44 and CD133 enriched cells, further enhancing tumor proliferation and malignant transformation." (PMID 39184916, 2024). "CP1-LVs adsorbed the most proteins in tumor tissues, especially the adsorption of OPN and CD44, similar to the results of in vitro incubation experiments, which could promote tumor cell internalization and may be beneficial to the delivery of nanovesicles to tumors." (PMID 38326312, 2024). "In particular, expression of CD44, a classical marker associated with epithelial-to-mesenchymal transition and poor prognosis of PDAC progression and metastasis, was found associated with Tumor 3 (3.6%, range 0.2-9.0% per PDAC), Tumor 4 (2.2%, range 0-10.0% per PDAC) and Tumor 7 subtypes." (PMID 39575252, 2024). "Moreover, mesenchymal tumor cells highly express CD44 mediating HA‐dependent iron endocytosis." (PMID 39007274, 2024). "Moreover, GFP+ CD44+ CCs were obtained and investigated 23 d after tumor transplantation." (PMID 38625488, 2024). "Therefore, CD44 could be a promising biomarker for clinical diagnosis, and targeting CD44 could be a treatment strategy for drug resistance and tumor metastasis." (PMID 38783892, 2024). "Previous studies have indicated that CD44 on tumor cells and CD11b on T cells can act as ligands for siglec-15, suggesting that siglec-15 may interact with different ligands from various cell types, further influencing its role in tumor progression and immune regulation." (PMID 38946426, 2024). "Additionally, CD44 expression profile within the immune microenvironment at a single-cell level, pseudotime trajectory of the CD44 gene and its role in cell communication, function of CD44 in tumor cell growth and migration, and the effect on macrophage polarization were analyzed." (PMID 38590654, 2024). "Furthermore, the recent association observed between CD44 and KRAS-dependent carcinomas and the potential correlations between CD44 and tumor mutational burden (TMB) and microsatellite instability (MSI) open new research scenarios for developing new strategies in cancer treatment." (PMID 38672650, 2024). "In addition, different induction conditions, accompanied by alternative splicing of CD44 isoforms, may lead to different expression of features in tumor cells." (PMID 38783892, 2024). "Therefore, CD44 is a crucial deactivation target for tumor therapy." (PMID 38903499, 2024). "Our previous comparative morphological study of BEN-associated tumors identified the sessile tumor architecture as a particular characteristic of these tumors, and this investigation detected that the solid growth of BEN tumors determined the loss of CD44 antigen." (PMID 38255201, 2024).
tumor (continued). "Therefore, CD44 has been considered as an essential target for tumor therapy." (PMID 39273139, 2024). "Therefore, we speculated that CD44 promotes the tumor immunosuppressive microenvironment by suppressing cytotoxic immune cells and promoting TAM infiltration." (PMID 38590654, 2024). "However, the level of CD44 on LSECs is significantly lower than that on tumor cells or tumor ECs." (PMID 38177179, 2024). "Notably, CD44 protein encapsulated in tumor-derived exosomes, which display that inherent enhanced organotropism may play a pivotal role in maintaining cancer progression, metastasis, and chemoresistance." (PMID 39766023, 2024). "In addition, miRNA-373 regulates the CD44 gene, which promotes tumor invasion and metastasis." (PMID 38540304, 2024). "Infusing NK cells from young mice could significantly increase the proportion of CD44+CTVlo OT-I cells and the expression level of CD44 in OT-I cells, which suggests that NK cell infusion could enhance the initial activation of tumor antigen-specific CD8+ T cells in aged mice." (PMID 38725070, 2024). "Moreover, PD-L1 blockade, CD4+ T cell depletion, or their combination not only increased the proportions of tumor-infiltrating CD44+CD69+CD8+ T cells but also elevated the proportions of central memory CD44+CD62L+CD8+ and effector memory CD44+CD62L−CD8+ T cells, compared with the control group." (PMID 36969495, 2023). "Therefore, the role of CD44 in maintaining stemness and the CSC function in tumor progression suggests that CD44 might be an important prognostic marker." (PMID 36831554, 2023). "Finally, in addition to its role as a predictive biomarker of poor prognosis and an independent predictor of tumor development, CD44 may be an effective therapeutic target." (PMID 36831554, 2023). "In view of PKMYT1AR function in NSCLC, the authors also targeted it in vitro and in tumor xenografts, showing that its inhibition through ASOs can efficiently impair tumor stem features, as self-renewal, and the expression of stem cell markers, as CD44 and SOX2." (PMID 36768150, 2023). "CD44, also being overexpressed in the resistant cells, is a cell-adhesion molecule known to interact with ezrin to form a complex that plays important roles in regulating tumour–endothelium interactions, cell migration, cell adhesion, tumour progression and metastasis." (PMID 37629086, 2023). "However, CD44 plays an important role in tumor progression and has the potential to be a tumor therapeutic target, which may warrant more in-depth research in tumor therapy in the future." (PMID 37711747, 2023). "Therefore, our results suggest that CD44 induced by malignant cells might downregulate tumor cells’ apoptosis, leading to a decline in growth inhibition and increased ability to resist chemotherapy." (PMID 36831554, 2023). "Moreover, CD44 ICD endows tumor cells with stemness and chemo/radio-resistance properties." (PMID 37894408, 2023). "Consequently, evaluation of CD44 expression in the tumor periphery using the P/C ratio may reflect the specificity of CD44 expression in the periphery much better than that of CD44 expression in the tumor periphery alone." (PMID 37760811, 2023). "Besides CD44, the tumor-suppressive action of extracellular ENO1 and MSN was mediated by Mtdh." (PMID 36923539, 2023). "Indeed, BCSC CD44+/CD24−/low/ALDH1+ phenotype is a very small population within the tumor." (PMID 36899854, 2023). "Also with human MPM cells, addition of anti-CD44 significantly decreased tumor cell proliferation." (PMID 37398648, 2023). "Indeed, it has been shown that CD44 isoforms promote cancer cell survival and invasion by interacting with other molecules in the tumor microenvironment, such as fibronectin and hyaluronic acid, which promote cancer cell survival, adhesion, migration, and invasion." (PMID 37287910, 2023).
tumor (continued). "Thus, stress-like tumor cells may suppress the antitumor function of CD44+ IgG1 PCs and promote tumor progression by secreting LAMB3." (PMID 37138324, 2023). "In addition, essential roles of CD44 in the cellular process of tumor invasion may be clarified and reveal the molecular mechanisms underlying GBM invasion." (PMID 37760811, 2023). "Also, tumor-derived EpCAM + CD44 + ALDHhigh cells showed elevated BMI1 expression." (PMID 37453969, 2023). "Taking the ratio of CD44 expression in the periphery to that in the core (P/C ratio) could more clearly represent the degree of CD44 expression in GSCs present within the invasive front of the tumor periphery." (PMID 37760811, 2023). "High expression of CD44 in BC is mainly linked with metastasis and not tumor initiation." (PMID 37445860, 2023). "Tumors that arose from the isolated population of CD44 + cells recreated the heterogeneity of the primary tumor and could be passaged multiple times, which proved that the CD44 + population had two key stem cell features—the ability for differentiation and self-renewal." (PMID 37453969, 2023). "Also, the overexpression of mouse CD44v6 or OPN enhances the growth of mouse stem-like tumor cells, and this growth may be dependent on the CD44/AKT pathway." (PMID 37835592, 2023). "Furthermore, CD44 overexpression was also associated with clinically poor prognostic features: older age, inoperable disease, stage IV at diagnosis, mutated BRAF, and high-grade tumor." (PMID 36831554, 2023). "Moreover, our results indicate that ICAM-1 may substitute for CD44 function as a coreceptor of receptor tyrosine kinase MET, and thus may compensate for CD44 loss during other tumor-relevant processes in Nf2-deficient livers." (PMID 37174657, 2023). "Additionally, HA could bind to highly expressed CD44 on tumor cells, promoting recognition and killing of tumor cells." (PMID 38033886, 2023). "Binding of cell surface glycoprotein CD44 to hyaluronic acid (HA) is a key event for mediating cell adhesion, motility, metastasis, inflammatory responses and tumor development, but the regulation mechanism and its molecular basis under diverse mechanical constraints remain unclear." (PMID 36768572, 2023). "Moreover, increased upregulation of tissue retention molecules VLA-1, CXCR6, CD103, and CD44 on lung CD8+ T cells following intranasal infection probably prevents the T cell migration to distal subcutaneous tumour site, thus permitting the uninhibited tumour growth." (PMID 36626205, 2023). "Furthermore, recent studies have highlighted CD44 as an important biomarker of cancer cell subpopulations and cancer stem cells (CSCs), exhibiting characteristics of self-renewal and tumor initiation, progression, invasion, metastasis, and recurrence, as well as chemo-/radiotherapy resistance." (PMID 37173926, 2023). "Studies in tumor tissues have indicated that CD44 plays a role as a cell surface receptor in processes like cell-cell interaction, adhesion, and migration, thereby facilitating the sensing and immune response to pathological lesions in the tumor microenvironment." (PMID 38145212, 2023). "Finally, we established subcutaneous xenotransplanted tumor models of CD44+EpCAM (high) cells." (PMID 36765401, 2023). "Therefore, we speculate that CD44 of tumor cells may affect the expression of CTLA-4 of T cells to help tumor cells immune evasion." (PMID 37316699, 2023). "CD44 exerts multiple molecular functions and may influence tumor cell behavior in several ways." (PMID 37174657, 2023). "Therefore, CD44 overexpression represents an unfavorable prognostic factor for CRC patients and could be used to predict tumor-associated poor prognostic features." (PMID 36831554, 2023). "This may help explain some contrasting results relative to the expression of CD44 in tumours." (PMID 37958796, 2023). "However, the authors did not observe an association between CD44 and tumour grade, lymphatic metastasis, response to chemotherapy, or disease-free survival." (PMID 38201468, 2023).